NOX4 (NADPH oxidase 4)
Diseases named in the same sentence as NOX4 in open-access papers (continued):
Sharing a sentence is not in itself a finding about the gene and the disease.
ischemia (32 papers, 2010 to 2025). A hypoperfusion of the BLOOD through an organ or tissue caused by a PATHOLOGIC CONSTRICTION or obstruction of its BLOOD VESSELS, or an absence of BLOOD CIRCULATION. "Nox4 deficiency attenuated ischemia-induced angiogenesis and potentiated responses to angiotensin II." (PMID 40725005, 2025). "In conclusion, HTK solution maintained high HIF-1α levels in a neurological cell ischemia study, associated with increased procaspase-3 production, suppressed procaspase-3 activation, and decreased NOX4 expression." (PMID 31504040, 2019). "Interestingly, it was reported that cardiac and systematic knockdown of Nox4 significantly reduced infarct size and area at risk after the ischemia–reperfusion challenge." (PMID 35890161, 2022). "Furthermore, a reduction in NOX-4 mRNA expression in skeletal muscle 3 days after hindlimb ischemia was observed in Trail−/− mice associating with impaired blood flow and capillary density." (PMID 28704938, 2017). "Indeed, Nox4 deficient mice develop less brain injury after focal ischemia as a result of reduced oxidative stress, neuronal apoptosis, and BBB disruption." (PMID 27014073, 2016). "Recent in vitro and in vivo studies demonstrate that NOX4 plays a key role in endothelial proliferation, adhesion, and revascularization following ischemia." (PMID 40725005, 2025). "Among various ROS-generating enzymes, NOX4 has been identified as a major source of ROS contributing to ischemia-induced oxidative stress and neuronal injury." (PMID 41375102, 2025). "Here, we investigated the therapeutic potential of a novel and specific NOX4 inhibitor during the reperfusion phase(s) following ischemia of the kidneys." (PMID 38671936, 2024). "Blocking NOX4 activation with Ferrostatin‐1 decreased ischemia‐induced neurological deficits and poor prognoses, which was similar to the effect of NBO on the prognoses." (PMID 35698913, 2022). "In femoral artery ligation mice model, NOX4-/- mice exhibit attenuated angiogenesis, while endothelial-specific NOX4 transgenic mice exhibit enhanced angiogenesis and blood flow recovery under ischemia in an eNOS-dependent manner." (PMID 34930338, 2021). "Physiological levels of NOX-4 have been implicated in the maintenance of vascular tone, inflammatory stress, and ischemia; however, when NOX-4 levels are increased, high levels of H2O2 and O2●− production have been registered." (PMID 33807637, 2021). "NOX4 mRNA was shown to be overexpressed in neurons and newly formed capillaries in the brain in an experimental mouse model of ischemia, which persisted up to one month after the onset of ischemia." (PMID 33953837, 2021). "Whereas the protective role of NOX4 in the chronically overloaded heart is well established, contrasting results have been reported on the role of NOX4 in ischemia/reperfusion (IR) injury." (PMID 32923955, 2019). "Nox4 KO reduced infract size after cardiac ischemia-reperfusion and Nox1/4 inhibitor administration played anti-inflammation via reducing ROS level in ischemia retina." (PMID 30571757, 2018). "The protective effects of NOX4 on ischemia-induced angiogenesis were also found in cultured aortae, in which NOX4 promoted aortic vessel sprouting and recovery of blood flow through PKA-dependent ERK activation." (PMID 28587189, 2017). "Altogether, these findings suggest that ischemia-induced activation of endothelial NOX4 promotes physiologic angiogenesis through the eNOS-dependent signaling, thereby enhancing vascular restoration." (PMID 28587189, 2017). "For example, local adenoviral NOX-4 injection 3 days prior to ischemia improved blood flow recovery and stimulated capillary density in mice 28 days after injury." (PMID 28704938, 2017). "NOX4 is also upregulated in neurons under ischemic conditions and plays a role in ischemia-induced brain angiogenesis." (PMID 28594389, 2017).
ischemia (continued). "In contrast, endothelial-specific NOX4 transgenic mice exhibit enhanced angiogenesis and blood flow recovery under ischemia in an eNOS-dependent manner." (PMID 28594389, 2017). "Application of the only validated low-molecular-weight pharmacological NADPH oxidase inhibitor, VAS2870, several hours after ischemia was as protective as deleting NOX4." (PMID 20877715, 2010). "Short reperfusion (25 min ischemia/1 h reperfusion) in NOX4-overexpressing mice led to increased infarct size and impaired energetics, whereas longer reperfusion (30 min ischemia/3–7 days reperfusion) in a similar model improved cardiac function and promoted reparative M2 macrophage polarization." (PMID 41009041, 2025). "Nox4 is extensively expressed in the central nervous system and growing evidences present that Nox4 acts as an important contributor to oxidative injury in pathophysiologic conditions such as ischemia, hemorrhage, and neurodegenrative processes." (PMID 37994671, 2024). "Moreover, findings suggest a cell type-specific function of NOX4 in ischemia, where an NOX4-dependent protective effect was observed in endothelial cells by promoting angiogenesis and attenuating inflammation." (PMID 38671936, 2024). "The present study showed that NBO maintained the balance of redox (elevating GPX4 and suppressing NOX4 expression), attenuated oxidase activity downstream (HO‐1) in ischemia‐affected astrocytes, and eliminated mitochondrial damage in the form of cytochrome c release into cytosolic fractions." (PMID 35698913, 2022). "NBO treatment significantly suppressed ischemia‐induced NOX4 activation." (PMID 35698913, 2022). "Upon ischemia, NOX4 is highly induced in both human and mouse brains." (PMID 33869275, 2021). "Blocking TGFβ1 inhibited the phosphorylation of VEGFR2 and eNOS in EWT murine ECs, suggesting the hypothesis that endothelial NOX4 mediated ischemia-induced angiogenesis through TGFβ1-dependent activation of eNOS." (PMID 28587189, 2017). "When the hearts were subjected to ischemia, NOX4 and p47phox were increased in the CT groups." (PMID 28036029, 2016). "Importantly, neuroprotection was preserved in old male and female Nox4−/− mice as well as in Nox4−/− mice subjected to permanent ischemia." (PMID 20877715, 2010). "Importantly, HOE642 treatment during in vitro ischemia reduced the NOX4 expression (p = 0.036)." (PMID 35440572, 2022). "Existing studies have shown that NOX4 induces the UPR in the ER and leads to cardiomyocyte death through CHOP in ischemia–reperfusion (IR) myocardial injury." (PMID 41154471, 2025). "The levels of GPX4 and NOX4 from ischemic tissues of NBO and normoxic rats were measured following 90‐min ischemia/24‐h reperfusion using western blotting." (PMID 35698913, 2022). "Together, these results suggested that NBO treatment retained the redox balance in astrocytes during the early phase of ischemia/reperfusion, by using the GPX4/NOX4 pathway." (PMID 35698913, 2022). "There is evidence that Ang II activates NOX4 via AT1 receptor pathway, which increases oxidative stress during ischemia." (PMID 29135932, 2017). "In NOX-1, NOX-2 but not NOX-4 knockout mice a significant decrease in the size of myocardial infarct was observed following 30 min of ischemia and 24 h of reperfusion." (PMID 39153251, 2024). "In endothelial cells, NOX4-derived H2O2 promoted proliferation and is activated by ischemia." (PMID 25296975, 2014). "To further investigate whether increased NOX4 activity is driving LCN2 expression in astrocytes, we tested the effect of NOX4 specific inhibitor GKT137831 on the expression of LCN2 protein in astrocytes subjected to in vitro ischemia." (PMID 35440572, 2022). "Moreover, the administration of this inhibitor to Nox4-deficient mice (who are protected themselves) conferred no further benefit, implying that VAS2870 protects against ischemia via inhibition of Nox4-NADPH oxidase." (PMID 27014073, 2016).
Insulin resistance (31 papers, 2016 to 2026). Increased resistance towards insulin, that is, diminished effectiveness of insulin in reducing blood glucose levels. "In this study, adipocyte-specific Nox4 deficient mice revealed delayed onset of diet-induced adipose tissue inflammation and insulin resistance." (PMID 37627585, 2023). "The promotion of mitochondrial oxidative stress associated with the deletion/inhibition of NOX4 in hepatocytes diminished insulin signaling, whereas NOX4 deficiency in vivo promoted hepatic and systemic insulin resistance, a key driver of NAFLD." (PMID 38060313, 2023). "After 12 weeks of HFD, NOX4-deficient mice displayed a complex phenotype with markedly elevated adiposity and insulin resistance accompanied by aggravated hepatic lipid accumulation." (PMID 35740032, 2022). "ROS in adipocytes is generated by NOX4 during adipogenesis causing insulin resistance and cell damage." (PMID 35911638, 2022). "However, NOX4 has also been demonstrated to cause insulin resistance and inflammation in adipose tissue." (PMID 39867658, 2024). "In contrast, deleting NOX4 specifically in adipocytes seems to reduce insulin resistance, possibly by limiting ROS-induced immune cell inflammation." (PMID 40943464, 2025). "It has been reported that NOX4 deletion in adipocytes delays adipose tissue inflammation and insulin resistance." (PMID 40141412, 2025). "Studies using global NOX4 knockout mice have shown an accelerated development of insulin resistance with a high-fat diet, likely due to a reduction in adipocyte numbers and increased adipocyte hypertrophy." (PMID 40943464, 2025). "ROS originating from Nox4 play a key role in adipogenesis and it has been shown that NOX4-derived ROS play a role in the onset of insulin resistance." (PMID 39576482, 2025). "As well, another important conclusion is that if the activity ratio GPx1/Nox4 is too high, the Nrf2-dependent stimulation of antioxidant protections is compromised, and insulin resistance develops." (PMID 37373256, 2023). "Deletion of Nox4 further facilitated the high-fat-diet-induced insulin resistance in adipose tissues." (PMID 37627585, 2023). "But another rationale comes from a recent and remarkable study which has shown that skeletal muscle NOX4 is responsible for adaptive responses to physical exercise that prevent the development of insulin resistance in mice." (PMID 37373256, 2023). "Substantial role of NOX4-derived ROS in the onset of insulin resistance and adipose tissue inflammation." (PMID 36359402, 2022). "Combined insulin and IGF-1 resistance restricted to the endothelium leads to a potentially favorable adaptation in contrast to pure insulin resistance, with increased Nox4-derived H2O2 generation mediating enhanced whole-body insulin sensitivity." (PMID 34420367, 2021). "Animal models of T2D indicate that antagonism of NOX1 and NOX2 restores endothelium-dependent vasodilation, while NOX4 has dynamic contributions to insulin resistance." (PMID 31382355, 2019). "In contrast, adipose-specific deletion of NOX4 prevented insulin resistance and inflammation in mice fed a high fat, high sucrose diet for 16 weeks." (PMID 31382355, 2019). "Whereas, NOX4 enhances insulin signaling via inhibition of PTP1B to counteract the onset of insulin resistance." (PMID 31382355, 2019). "Furthermore, NOX4 is known to promote the oxidation of glucose and fatty acids, as well as preserving exercise capacity and counteracting insulin resistance." (PMID 40692696, 2025). "Nox4 in skeletal muscle tissue facilitates ROS-mediated adaptive responses, promoting muscle function, maintaining redox balance, and preventing the development of insulin resistance." (PMID 38721062, 2024). "Interestingly, NOX4 has been shown to improve high-fat diet-induced adipose accumulation, insulin resistance, and liver steatosis." (PMID 39867658, 2024).
Insulin resistance (continued). "Catalpa, a bioactive ingredient in Zantedeschia rehmannii root, can not only improve liver insulin resistance by acting on AMPK/NOX4/PI-3 K/AKT pathways but also improve HFD-induced insulin resistance in mice by reducing adipose tissue inflammation and inhibiting JNK and NF-κB pathways." (PMID 36733419, 2023). "However, considering the vasoprotective effects of NOX4, these findings provide opportunities for future studies to target NOX4 for mitigation of insulin resistance." (PMID 31382355, 2019). "This suggests that NOX4 may be upregulated during the onset of insulin resistance as a protective mechanism." (PMID 31382355, 2019). "The distinct subcellular localization of NOX4 compared with other NOX isoforms may explain the differing functions of NOX4 throughout insulin resistance progression." (PMID 31382355, 2019). "While adipose-specific deletion of NOX4 attenuated adipose tissue inflammation and the early onset of insulin resistance in diet-induced obese mice, suggesting that NOX4 derived oxidative stress and ROS production plays a role in the development of insulin resistance in adipose tissue." (PMID 30577684, 2018). "NOX4 overexpression reported in excessive food intake reduced PTP1B inhibition and enhanced insulin resistance in adipocytes." (PMID 40141412, 2025). "In the esophagus, coordinated changes in methylation and expression implicate MSTN in metabolic adaptation and immune regulation, potentially via AMPK/NOX4/PI3K/AKT signaling, which has established links to glucose homeostasis and insulin resistance." (PMID 40699830, 2025). "Previously we have shown that NFE2L2 drives Nox4 expression in muscle and, in turn, that NOX4-derived H2O2 enhances NFE2L2 antioxidant defense to attenuate muscle oxidative damage and insulin resistance." (PMID 38060313, 2023). "We have shown that mitochondria- and NOX4-derived ROS drive NFE2L2 antioxidant defense in hepatocytes to limit the oxidative damage of macromolecules, the development of insulin resistance, and the progression to NASH and fibrosis." (PMID 38060313, 2023). "Downregulation of ASM increases GLUT4 expression and decreases Nox2- and Nox4-dependent superoxide anion generation in cultured rat aortic endothelial cells, suggesting that high ASM levels are responsible for endothelial insulin resistance." (PMID 33850277, 2022). "Increased Nox4-dependent production of superoxide anions reduces GLUT4 expression and impairs glycolysis in rat aortic endothelial cells challenged with palmitic acid, a saturated free fatty acid that induces insulin resistance." (PMID 33850277, 2022). "These NOX4 KO mice also gained body weight throughout the intervention, suggesting that NOX4 may convey elevations in blood glucose regardless of adiposity during the initial development of insulin resistance." (PMID 31382355, 2019). "Enhanced NOX4 mRNA levels and H2O2 production were also observed in adipose tissue of obese mice with metabolic syndrome, which is in agreement with the suggestion that NOX4 may contribute to insulin resistance." (PMID 31382355, 2019). "Therefore, we reasoned that ablating NOX4 and abrogating the resultant H2O2-dependent NFE2L2 antioxidant defense response, and, in particular, reducing SOD2, would promote mitochondrial oxidative stress to diminish insulin signaling and promote insulin resistance." (PMID 38060313, 2023).
ischemic stroke (31 papers, 2010 to 2025). A stroke disorder caused by obstruction of blood flow to the brain, due to thrombotic (local blood clot formation) or embolic (due to a blood clot or other material traveling from another site) event. "Emerging data suggest that NOX4 is significantly associated with ischemic stroke, particularly by increasing levels of oxidative stress." (PMID 35154560, 2022). "In addition, the NOX4 rs11018628 polymorphism has been correlated with short-term recovery and decreased risk of ischemic stroke, but the molecular mechanism of this phenomenon remained to be unveiled." (PMID 35154560, 2022). "Animals deficient in NOX4 are strongly protected from ischemic stroke." (PMID 33869275, 2021). "NOX4 has also been shown to have a protective effect on ischemic stroke; NOX4-deficient mice had reduced infarct size and improved neurological outcome after ischemic stroke." (PMID 26941888, 2016). "This indicates a strong association between olmesartan treatment and the inhibition of NOX4 expression, consistent with its therapeutic potential in reducing oxidative stress after ischemic stroke." (PMID 39334724, 2024). "Several studies have revealed that NOX4 leads to ischemic stroke via BBB breakdown and neurodegeneration." (PMID 35154560, 2022). "A growing number of studies have shown that NOX4 levels dramatically correlate with ischemic stroke." (PMID 35154560, 2022). "With an improved understanding of the pathogenesis and molecular mechanism of ischemic stroke, NOX4 appears to be an important regulator of ischemic stroke pathophysiology." (PMID 35154560, 2022). "In this review, we explored basic information about MAGI2-AS3 and its subcellular location and summarized the literature describing the relationship between NOX4 and ischemic stroke, specifically its pathophysiological mechanism." (PMID 35154560, 2022). "While expression levels of NOX4 are typically elevated in the normal kidney, artery, lymph node, adipocyte, breast, and brain tissue, high NOX4 levels in the brain contribute to ischemic stroke." (PMID 35154560, 2022). "In this review, we summarize the subcellular location, expression, and pathophysiological mechanisms of NOX4 in the occurrence and development of ischemic stroke." (PMID 35154560, 2022). "Nicotinamide adenine dinucleotide phosphate oxidase 4 (NOX4) is most closely related to the formation of ROS during ischemic stroke." (PMID 35154560, 2022). "NOX4-generated ROS has played a significant role in the initiation and development of various human diseases, including ischemic stroke." (PMID 35154560, 2022). "It traverses the intact BBB, transports without degradation, to be widely distributed in microglia, neurons and astroglia in the CNS, and is delivered in sufficient quantities to knockdown NOX4 and alleviate ischemic stroke." (PMID 33869275, 2021). "A twelve-amino acid peptide that transcytoses the BBB, termed MTfp, was chemically conjugated to siRNA to create a novel peptide-oligonucleotide conjugate (POC), directed to downregulate NOX4, a gene thought responsible for oxidative stress in ischemic stroke." (PMID 33869275, 2021). "Previous studies have shown that the expression of NOX4 in ischemic stroke and traumatic brain injury is closely related to the severity of SBI." (PMID 33281556, 2020). "It has been reported that the induction of NOX4 is closely related to the destruction of the blood-brain barrier in ischemic stroke." (PMID 33281556, 2020). "In an ischemic stroke animal model, administering VAS2870 intrathecally several hours after cerebral ischemia offered the same protection as deletion of NOX4, which was implicated as the source of ROS in this particular model." (PMID 28095923, 2017). "In analysis of whole brain tissues, the mRNA and protein levels of NOX2 and p22phox increase in the ischemic hemisphere in a rat model of MCAO, and NOX4 protein increases in the ischemic cortex and basal ganglia after ischemic stroke in mice." (PMID 26941888, 2016).